OGT (O-linked N-acetylglucosamine (GlcNAc) transferase)
Diseases named in the same sentence as OGT in open-access papers (continued):
Sharing a sentence is not in itself a finding about the gene and the disease.
cancer (continued). "Recently, it has been reported that O-GlcNAcylation plays a role in enhancing HCC formation in mice via a high dietary fructose intake; this implies that OGT is important in promoting cancer cell survival." (PMID 39984455, 2025). "Subsequent functional experiments with NSCLC cell lines and organoids validated that mannose can inhibit cancer cell growth by targeting the OGT/hnRNP R/JUN/IL-8 axis." (PMID 39990658, 2025). "For example, investigations in obese tissues and cancer cell lines show a positive correlation between O-GlcNAcylation and mTOR phosphorylation, while OGT inhibition in cortical neurons increases autophagy markers via mTOR inhibition." (PMID 41101503, 2025). "The result showed that OGT expression levels were significantly higher in cancer tissues compared to adjacent normal tissues." (PMID 38778217, 2024). "Based on this, OGT and O-GlcNAcylation inhibition have been proposed as potential therapeutic approaches for the treatment of cancer." (PMID 38718861, 2024). "In cancer, OGT facilitates tumor cell growth and survival, enhances invasion and metastasis, modulates the tumor microenvironment (TME), contributes to chemoresistance, and affects gene expression and epigenetics." (PMID 39487556, 2024). "This review outlines the biochemical functions of OGT and summarizes its role and specific mechanisms in tumors, aiming to provide new insights and approaches for treating malignant tumors." (PMID 39285476, 2024). "Cancer cells also show increased OGT expression, which increases O-GlcNAcylation and promotes cancer cell proliferation and resistance to chemotherapy." (PMID 38718861, 2024). "Previous studies reported OGT was involved in tumor formation and metastasis via regulating autophagy or ferroptosis in several cancers." (PMID 38973004, 2024). "Cancer cells usually have high OGT levels but low OGA expression levels, and elevated O-GlcNAcylation appears to be a general characteristic of cancer cells." (PMID 39178944, 2024). "Small-molecule inhibitors of OGT or OGA have been developed to combat various types of cancers both in vitro and in vivo." (PMID 39178944, 2024). "Given the attractiveness of OGT as a potential molecular target for cancer treatment, several small molecule inhibitors of OGT (OGTi) have been developed." (PMID 39413067, 2024). "Recent studies observed increased OGT and O-GlcNAcylation levels in a broad range of human cancer tissues compared to adjacent normal tissues, indicating a universal effect of OGT in promoting tumorigenesis." (PMID 38168435, 2024). "On the other hand, mTOR can regulate protein O-GlcNAcylation in cancer cells through the stabilization of OGT." (PMID 39178944, 2024). "Knockdown of OGT reduced cancer cell sensitivity to 5-FU by lowering both TS protein levels and activity." (PMID 39285476, 2024). "ECSCs can be protected by OGT in exosomes through PD-1 upregulation, leading to the promotion of cancer immunosuppression." (PMID 39199296, 2024). "Many efforts have been made to develop therapeutic options for cancer through the manipulation of the O-GlcNAcylation of proteins, primarily using specific inhibitors of OGT or OGA." (PMID 39178944, 2024). "The increasing body of research on the impact of O‐GlcNAc modification in tumourigenesis has positioned the utilisation of OGT inhibitors as a pivotal aspect in cancer therapeutics." (PMID 39358921, 2024). "This demands cancer cell specific suppression of OGT through optimizing the dose range of OGT inhibitors and/or genetic targeting of OGT in cancer cells." (PMID 38718861, 2024). "In cancer cells, O-GlcNAc and its enzyme OGT are highly elevated, thus coupling the alteration in nutrient status to signaling activities, contributing to reprogramming cellular metabolism and cancer progression." (PMID 39337387, 2024).
cancer (continued). "O-GlcNAcylation and expression of O-GlcNAc transferase (OGT), the enzyme responsible for catalyzing O-GlcNAcylation, have been reported to be elevated in various cancer types, including CRC." (PMID 38473392, 2024). "OGT is vital for cell division, as its inhibition results in cell death, thereby rendering it unsuitable as a target for diseases, including cancer therapy." (PMID 39766284, 2024). "A previous study identified a critical role of OGT in promoting CSCs phenotype, and tumor initiation, potentially via upregulating cancer stem cell factors and upregulation of KLF8 levels." (PMID 37152043, 2023). "Protein O-GlcNAcylation is catalyzed by the enzyme O-GlcNAc transferase (OGT), an effector of hexosamine biosynthesis pathway that is found to be upregulated in most cancers." (PMID 37689115, 2023). "Multiple proteins involved in ferroptosis or regulation of ferroptosis are regulated by OGT and O-GlcNAc in cancer." (PMID 37838167, 2023). "Other reports have also shown the importance of OGT and O-GlcNAc in mediating chemotherapy resistance in cancer." (PMID 37838167, 2023). "Treatment with OGT inhibitor shows a remarkable increase in the sensitivity of cancer cells to doxorubicin-induced apoptosis." (PMID 37838167, 2023). "In some cancer models, this regulation appears to be lost, and, as a result, high O-GlcNAc, OGT, and HBP enzyme abundance are observed." (PMID 37949223, 2023). "The activity of mTOR signaling in hepatocarcinoma cells is upregulated by OGT and O-GlcNAc to drive cancer cell proliferation." (PMID 37838167, 2023). "Together, these findings support the potential of using an OGT inhibitor in combination with other therapeutic agents to enhance the efficacy of current cancer treatments." (PMID 37838167, 2023). "The expression and activity of proteins involved in the MEK/ERK pathway have been reported to be modulated by OGT and O-GlcNAc in cancer." (PMID 37838167, 2023). "Together, these findings reveal the extensive crosstalk between OGT and mTOR pathway and their role in regulating cancer cell proliferation and tumor growth." (PMID 37838167, 2023). "The expression of OGT promotes the growth of cancer stem cells (CSC) in colon cancer, whereas OGA inhibits this growth." (PMID 37107691, 2023). "The level and function of OGT and O-GlcNAc in cancer cells are also modulated by the MEK/ERK pathway." (PMID 37838167, 2023). "In cancer cells, β-catenin is directly modified by OGT at Threonine residue 41, which increases the stability of the protein contributing to drive cancer cell proliferation." (PMID 37838167, 2023). "OGT and O-GlcNAc are also critical for the expression of cancer stem-like cell markers, such as CD44 and CD133 in colon cancer." (PMID 37838167, 2023). "Combined treatment with OGT inhibitor and Doxorubicin notably increases the percentage of cancer cells undergoing apoptosis, reduces cancer cell proliferation, and impairs tumor growth in vivo." (PMID 37838167, 2023). "Increased levels of cyclin D1 in cancer cells with high levels of OGT/O-GlcNAc results in an increase in cell proliferation." (PMID 37838167, 2023). "Together, these findings help establish an extensive interconnection between OGT/O-GlcNAc and the Hippo pathway to regulate cancer cell survival and tumor growth." (PMID 37838167, 2023). "In this section, we will extensively discuss the latest findings on the role of OGT and O-GlcNAc in cancer." (PMID 37838167, 2023). "The data in this report implicate roles of OGT and O-GlcNAc within a pathway leading to cancer stem-like cell (CSC) expansion." (PMID 37231419, 2023). "Cancer cells with reduced OGT level showed significant reduction in lipid metabolites and lipid-synthesis-associated metabolites." (PMID 37838167, 2023). "O-GlcNAc transferase (OGT) has been found to regulate many biological processes, including transcription, immune response, neurodegeneration, metabolism, and cancer." (PMID 36626982, 2023).
cancer (continued). "The stability of PD-L1 in cancer cells increases with elevated levels of O-GlcNAc and decreases with the reduction in the level of O-GlcNAc, suggesting that OGT/O-GlcNAc regulates PD-L1 stability." (PMID 37838167, 2023). "Similar to the regulation of the MEK/ERK pathway in cancer, the PI3K/Akt pathway, another major pathway in cancer, is also regulated by OGT and O-GlcNAc." (PMID 37838167, 2023). "In cancer cells, glucosamine has been reported as a substrate for protein O-GlcNAcylation by O-GlcNAc transferase (OGT), and O-GlcNAcase (OGA) can remove the O-GlcNAc modification." (PMID 37009898, 2023). "Studies have noted that decreasing the level of O-GlcNAc using inhibitors or genetic knockout of OGT would promote apoptosis in cancer cells." (PMID 36980207, 2023). "Both O-GlcNAc and its enzyme OGT are highly elevated in cancer and fulfill the crucial role in regulating many hallmarks of cancer." (PMID 37838167, 2023). "Inhibition of OGT also leads to reduced cancer stem-like cell populations and self-renewing capacity in leukemia, potentially via regulation of STAT3/5 signaling." (PMID 37838167, 2023). "Although certain connections between OGT/O-GlcNAc expression and amino acid metabolism and their role in cancer have been explored, further investigation is required to generate a more comprehensive understanding of these mechanisms." (PMID 37838167, 2023). "The expression of OGT is found to be increased in a wide variety of cancers whereas misexpression (both upregulation and downregulation) of OGA is also similarly reported." (PMID 37689115, 2023). "Genetic or pharmacological inhibition of OGT decreases cancer stem-like cell populations as well as the expression of transcription factors involved in promoting self-renewing capacity." (PMID 37838167, 2023). "Together, these findings reveal a significant contribution of OGT and O-GlcNAc in promoting cancer cell survival during chemo- and immunotherapy and contributes to avoiding immune destruction." (PMID 37838167, 2023). "This increase in O-GlcNAcylation level, together with increased OGT expression, promotes cancer cell proliferation, survival, chemoresistance, stem-like cell phenotypes, invasion, and metastasis." (PMID 37838167, 2023). "A similar regulation is also observed in esophageal squamous cell carcinoma, where ERK increases OGT expression driving cancer cell proliferation." (PMID 37838167, 2023). "The regulation of metastasis by OGT and O-GlcNAc occurs not only in cancer cells but also in other cells that contribute to the tumor microenvironment." (PMID 37838167, 2023). "In fibrosarcoma cells, pharmacological or genetic inhibition of OGT increases the expression of p21 impairing cancer cell proliferation." (PMID 37838167, 2023). "Together, these studies reveal the regulation of de novo lipid synthesis by OGT/O-GlcNAc in cancer cells." (PMID 37838167, 2023). "Collectively, these findings reveal significant interactions between OGT/O-GlcNAc expression and the Wnt/β-catenin pathway and their role in regulation of cancer cell growth and survival." (PMID 37838167, 2023). "Recent studies have started to connect the regulation of cancer stem-like cells to OGT and O-GlcNAc." (PMID 37838167, 2023). "In the case of tumor biology, OGT and O-GlcNAc are upregulated in many cancer types, including bladder cancer, breast cancer, and lung cancer." (PMID 36626982, 2023). "OGT and O-GlcNAc can significantly contribute to modulating the metastasis potential of cancer cells." (PMID 37838167, 2023). "Rescue of OGT inhibitor effects of cancer stem-like cell reprogramming was performed by MBD2_v2 overexpression, further solidifying the upstream regulatory placement of OGT in this pathway." (PMID 37231419, 2023).
cancer (continued). "Previous discussion has highlighted the crucial role of OGT and O-GlcNAc during tumor progression and the potential for OGT/O-GlcNAc as a therapeutic target in cancer treatment." (PMID 37838167, 2023). "In this review, we present and discuss the latest findings elucidating the involvement of OGT and O-GlcNAc in cancer." (PMID 37838167, 2023). "In recent years, there has been a growing understanding of how OGT and O-GlcNAc regulate cancer cell proliferation and survival, metastasis, drug resistance, and other cancer-associated phenotypes." (PMID 37838167, 2023). "Because of this, OGT is recognized as a critical nutrient sensor in animal physiology, particularly in development, cancer, and metabolic disease." (PMID 36951889, 2023). "Inhibition of Cathepsin-B O-GlcNAcylation impairs metastasis of cancer cells, indicating a critical role of OGT and O-GlcNAc in remodeling the tumor microenvironment to support invasion and metastasis." (PMID 37838167, 2023). "In general, O-GlcNAcylation activation in cancer cells can be catalyzed by O-GlcNAc transferase (OGT), whereas O-GlcNAcylation is suppressed by O-GlcNAcase (OGA)." (PMID 35795059, 2022). "For the three cancers, SNVs were more likely to be detected in the high-OGT expression group than in the low-OTG expression group, and the top five genes with the highest frequency of SNV were MUC17, PIK3CA, SI, SYNE1, and PTEN." (PMID 35356257, 2022). "Initially, we failed to collect enough samples to verify the mRNA and protein levels of OGT in cancers of the pan-cancer analysis and the relevance of OGT with the prognosis." (PMID 35356257, 2022). "Emerging evidence also shows that OGT is involved in regulating/activating cancer stem cell potential and resistance in anti-cancer treatments." (PMID 36291918, 2022). "The same is true for human neuronal cells and cancer cells, probably because of OGT upregulation when Glu is scarce." (PMID 35931119, 2022). "Increased OGT expression and protein O-GlcNAcylation have been observed in numerous cancer cells, including gastric, breast, lung, prostate, colon, liver, bladder, ovarian and endometrial cancer cells." (PMID 35296731, 2022). "The prognosis significance of OGT expression in pan-cancer was also supported by the Kaplan–Meier curves." (PMID 35356257, 2022). "Analysis of clinical specimens found that high SAM68 expression was associated with late cancer stages, and patients with high-OGT/high-SAM68 expression in their tumors had poorer overall survival compared to those with low-OGT/low-SAM68 expression." (PMID 35008409, 2022). "In either setting, we conclude that p21 levels induced by OGT inhibition correlate with cell cycle arrest and decreased cancer cell proliferation." (PMID 35868563, 2022). "Collectively, we determined the different OGT expressions and their significant clinical values in various cancers." (PMID 35356257, 2022). "There is a positive correlation between OGT and proteasome subunits expression in clinical cancer samples including breast invasive carcinoma and colorectal adenocarcinoma." (PMID 36059648, 2022). "highlights the potential of OGT inhibitors in combination with other therapies to benefit cancer-specific vulnerabilities and reports a novel synthetic lethal interaction between OGT and CDK9 inhibitors." (PMID 36439421, 2022). "Another study of PPI networks predicted OGT as a key cancer “hub” gene making extensive interactions with other proteins." (PMID 36291918, 2022). "For the first time in the field, we have provided an overview of OGT in 32 cancers using a large number of samples (n = 21,196), determining distinct OGT expression in 25 cancers and its prognosis effects in 12 cancers." (PMID 35356257, 2022). "Diverse (increased) expression levels of OGT showed clinical associations in SCLC, similar to the results for pan-cancer." (PMID 35356257, 2022).
cancer (continued). "Dysregulated O‐GlcNAc modification has been commonly observed in various cancer cells, and OGT has been proposed as a novel therapeutic target for cancer treatment." (PMID 35347892, 2022). "Many studies have investigated the effects of aberrant OGT/OGA expression on global O-GlcNAcylation activity in cancer cells." (PMID 36291918, 2022). "The results showed that OGT was dysregulated in many cancer types, with OGT being significantly higher in PC tissues\ (n=497) than in normal tissues (n=52)." (PMID 36439421, 2022). "Dysregulation of the sole enzymes responsible for O-GlcNAc cycling, O-GlcNAc transferase (OGT) and O-GlcNAcase (OGA), and the associated cellular O-GlcNAc profile is a common feature across nearly every cancer type." (PMID 36291918, 2022). "In this context, increased levels of O-GlcNAcylation, OGT or GFAT in cancer patients are correlated with cancer progression and a poor prognosis." (PMID 34974534, 2022). "O‐GlcNAc is a common modification that regulates the stability, trafficking, and function of many proteins and OGT, the sole enzyme known to catalyze O‐GlcNAcylation, is indispensable for the proliferation of all 975 cancer cell lines in the DepMap database." (PMID 35514210, 2022). "Pharmacological inhibition of OGT or GFAT suppresses cancer progression and enhances cellular sensitivity to anticancer agents." (PMID 34974534, 2022). "As the overall elevations in O-GlcNAcylation is recognized as a common feature of cancer cells, OGT is positioned as a novel therapeutic target with potent anti-glycolytic activity." (PMID 36439421, 2022). "As previously reported that aberrant PPIs underlie the etiology of cancer, decoding the molecular connections of dysregulated OGT/OGA–protein networks in cancer will be important for therapeutic innovations." (PMID 36291918, 2022). "For the first time in the field, we provide an overview of OGT in 32 cancers using a large number of samples (n = 21,196), determining distinct OGT expression in 25 cancers and its prognosis effects in 12 cancers." (PMID 35356257, 2022). "Previous studies showed that high expression of OGT was related to drug resistance and poor prognosis of several kinds of cancers." (PMID 36439421, 2022). "Low OGT activity promotes c-MYC degradation to maintain survival in low glucose of cancer cells that were killed when O-GlcNAcylation was increased by the OGA inhibitor PUGNAC." (PMID 34868034, 2021). "OGT promotes protein O-GlcNAcylation and has been found to be upregulated in most cancers including ESCC." (PMID 34354953, 2021). "One of the key regulators contributing to OGT overexpression is the hyperactive Erk signaling cascade in cancer." (PMID 34354953, 2021). "For example, FOXA1 and FOXA2, both of which play an important role in α-cell glucagon biosynthesis and secretion, are O-GlcNAc modified by OGT in cancer cells, and this modification is important for the stability of the protein." (PMID 33460647, 2021). "In rapidly dividing tissue, the loss of OGT or OGA is lethal, making both enzymes attractive cancer therapy targets." (PMID 33916244, 2021). "The high OGT activity in cancer cells would enhance O-GlcNAcylation of the c-myc oncoprotein and stabilize c-myc to promote cancer cell transformation and metastasis." (PMID 34638625, 2021). "Clinically relevant HBP and OGA inhibitors are already available and OGT inhibitors are in development to modulate O-GlcNAcylation as a potentially novel cancer treatment." (PMID 34868034, 2021). "OGT influenced HIF1a stability by controlling levels of αKG in cells as decreasing O-GlcNAcylation in cancer cells increases αKG and HIF-1α hydroxylation, leading to enhanced proteasomal degradation." (PMID 33154167, 2021). "This study aimed to find conditions that maximize the therapeutic effect of cancer and minimize tissue damage by combining an OGT inhibitor (OSMI-1) and tumor necrosis factor-related apoptosis-inducing ligand (TRAIL)." (PMID 34681736, 2021).